CDC25B (cell division cycle 25B)
Diseases named in the same sentence as CDC25B in open-access papers (continued):
Sharing a sentence is not in itself a finding about the gene and the disease.
cancer (62 papers, 2001 to 2025). A tumor composed of atypical neoplastic, often pleomorphic cells that invade other tissues. "Overall, understanding the mutation profile of CDC25B can help us to provide new targets for cancer treatment as well as personalized health management and prevention strategies for high-risk populations based on the mutation profile of CDC25B." (PMID 39371450, 2024). "• Caused mouse cancer cells to enter a G2/M phase of cell cycle arrest in vivo.• Prevented the CDC25B substrate, CDK1 from being dephosphorylated." (PMID 38606093, 2024). "Previous analyses had shown that increased Cdc25B caused diverse and sometimes opposite effects in different cancer cells." (PMID 33745968, 2021). "To reveal the impact of increased Cdc25B in tumorigenesis, we first analyzed the association of CDC25B expression to survival of cancer patients." (PMID 33745968, 2021). "Excess Cdc25B has been implicated in having a function as an oncogene that impacts positively to cancer cell progression during tumorigenesis." (PMID 33745968, 2021). "Increased Cdc25B levels are often detected in cancer cell lines and human cancers and have been implicated in contributing to tumor growth, potentially by providing cancer cells with the ability to bypass checkpoint controls." (PMID 33745968, 2021). "The CDC25A and CDC25B isoforms are overexpressed in primary tissue samples from various human cancers, which is strongly associated with tumor aggressiveness and poor prognosis." (PMID 26880913, 2016). "Overexpression of CDC25 phosphatases also occurs at a high rate in a wide range of cancers, and the CDC25B isoform in particular, is associated with more aggressive disease." (PMID 23840880, 2013). "As shown in, 9 essential oil compositions could act on CASP3, MAP2K1 and CDC25B, respectively and be associated with solid tumor/cancer." (PMID 35702766, 2023). "Three CDC25 isoforms exist in mammalian cells and their overexpression, particularly CDC25A and B, are commonly reported in a wide variety of human cancers, with CDC25B overexpression in particular, being associated with more advanced disease and poor clinical outcome (reviewed in 12–14)." (PMID 23840880, 2013). "Real-time q-PCR and protein immunoblotting (Western blot) confirmed that CDC25B expression was significantly upregulated in cancer tissues compared with paracancerous tissues in clinical samples." (PMID 39371450, 2024). "Representative immunostaining from cancer sample sections confirmed that the levels of KI-67, a cell proliferation marker, and CDC25B, the FOXM1 downstream target gene, were dramatically down-regulated." (PMID 37344857, 2023). "To understand the regulatory mechanism of FOXM1a in cancer cell proliferation and tumorigenesis, we analyzed the effects of FOXM1a on the expression of FOXM1c target genes, including CDC25B, PLK1, and CCNB1, which are essential for cell proliferation." (PMID 37759731, 2023). "Enhanced m6A modification mediated by METTL3 accelerates translation of CDC25B and increases the proportion of tumor cells in G2/M stage, leading to malignant cancer growth." (PMID 37996892, 2023). "CDC25B is a key player in G2/M cell cycle progression and well known to be upregulated in various cancers, but the specific mechanisms of CDC25B in tumor progression is still uncertain as with the other 3 molecules." (PMID 35841085, 2022). "Previous studies also have shown that CDC25B plays a critical role in the G2-to-M phase transition 30, as well as cancer progression." (PMID 35637959, 2022). "Cdc25B is overexpressed solely in Gastric (78%) endometrial (73%) and prostate (30%) cancers and Gliomas (47%)." (PMID 35458583, 2022).
cancer (continued). "The potential of these 4 molecules as a novel drug target also has been shown in a variety of studies: An accumulated knowledge on AGR2, PDE4D, NINJ2 and CDC25B have accelerated the drug discovery targeting these molecules in the other cancers." (PMID 35841085, 2022). "Here we analyzed The Cancer Genome Atlas (TCGA) database and found that patients with high CDC25B expression had the expected poor survival." (PMID 33745968, 2021). "CDC25B is an important regulator of cell cycle progression and is overexpressed in many cancer types, and it directly binds to miR-148b-3p." (PMID 34346842, 2021). "The results suggest that high CDC25B expression impacts negatively to the overall survival of cancer patients, consistent with the expected oncogenic role of CDC25B." (PMID 33745968, 2021). "We found that FDI-6 and FOXM1 shRNA impaired Olaparib-induced expression of CDK1, CCNA1, CCNB1, and CDC25B to inhibit the mitosis of cancer cells." (PMID 34880209, 2021). "The increased Cdc25B is then oncogenic that it enhances cancer cell proliferation through bypassing checkpoint control." (PMID 33745968, 2021). "Cell division cycle 25B (CDC25B) is involved in cell cycle regulation and is highly expressed in many malignant tumors." (PMID 31856414, 2020). "In accordance with their critical roles in cell cycle regulation, CDC25A and CDC25B have been shown to be involved in cancer progression." (PMID 33385163, 2020). "The transcription levels of MAPK14 and CDC25B in 72 pairs of ccRCC and adjacent healthy tissues from the cancer genome atlas database and the protein expression levels in 66 pairs of clinical samples were analyzed in this study." (PMID 31856414, 2020). "Overexpression of CDC25, particularly CDC25A and CDC25B, has been observed in a variety of human cancers and correlates with poor clinical prognosis." (PMID 30718768, 2019). "CDC25B is known to be able to activate the serine/threonine kinase AKT in cancer cells treated with the mTOR inhibitor, rapamycin." (PMID 31024841, 2019). "Several other proteins such as AURKA, AURKB, CHEK1, BIRC5, CDC25B decreases their local PageRanks in cancer which means they become more controlled." (PMID 29370181, 2018). "FOSL1, BCL2, CDK6, IL7R, RUNX2 and CDC25B have been shown to be targets of JQ1 for transcriptional silencing in other types of cancers." (PMID 27764802, 2016). "CDC25B overexpression has been documented in a variety of human cancers, including head and neck and colon, and non-small cell lung cancer validates its oncogenic potential." (PMID 26880913, 2016). "CDC25B is an important regulator of cell cycle progression and is overexpressed in many cancer types." (PMID 27586591, 2016). "MAP2K4, and MAPKAPK2 belong to the MAPK family, which is involved in cell proliferation, differentiation, and apoptosis, while CDC25B plays an important role in cell cycle, and is deregulated in several types of cancer." (PMID 27821810, 2016). "In a cell-free experiment, it inhibited the activity of Cdc25B and C directly 42, and it was also shown to alter the expression profile of the active or inactive form of Cdc25C in different cancer cell lines 35,43,44." (PMID 26228523, 2015). "Such “onco-miRNAs” have also been demonstrated in PDAC: miR-196a promotes cancer progression by targeting NFKBIA, and miRNA-126 and 148a inhibit cancer cell growth by down-regulating CDC25B and ADAM9, respectively." (PMID 25742499, 2015). "We report that overexpression of CDC25B, as is commonly found in human cancer, results in a significant increase in centrin 2 at the centrosomes of interphase cells." (PMID 23840880, 2013). "For example, Cdc25a, Cdc25b and Cdc25c, members of the Cdc25 family, are significantly co-expressed (p < 10-6) with the cancer-related genes." (PMID 23039964, 2012). "Elevated expression of CDC25B has been documented in a growing list of human cancers suggesting a potential role in the alteration of molecular processes leading to oncogenesis." (PMID 20128929, 2010).
cancer (continued). "Since abnormal expression of CDC25B has been found in numerous cancers our results provide new insights into the molecular mechanisms of the involvement of this phosphatase in tumorigenesis." (PMID 20128929, 2010). "CDC25B, CDC25C and phospho-CDC25C (Ser216) expression were associated with malignant features and aggressive cancer phenotypes." (PMID 20500813, 2010). "CDC25B, CDC25C and phospho-CDC25C (Ser216) were associated with malignant features and aggressive cancer phenotypes." (PMID 20500813, 2010). "Previously, a wide range of CDC25B overexpression (20-79%) has been reported in many other cancer types." (PMID 20500813, 2010). "It is thus suggested that the reduced expression of cdc25B in dedifferentiated carcinoma is unique compared to other cell cycle regulatory proteins." (PMID 12085185, 2002). "In this study, therefore, we investigated the expression of cdc25A and cdc25B in order to elucidate the role of these proteins as modulators of the cell cycle progression of this carcinoma." (PMID 12085185, 2002). "CDC25B/C exhibited strong staining in cancer tissues, indicating high expression." (PMID 40216745, 2025). "CDC25B is overexpressed in tumor cells and is an important driver of various cancers." (PMID 36713456, 2022). "CDC25B has been widely confirmed to promote cancer by activating Cyclin/CDK." (PMID 35743699, 2022). "Thus, although the reason is still unclear to us, it is likely that more factor is required for this cancer-type-specific tumor suppressive function of Cdc25B." (PMID 33745968, 2021). "CDC25B has been reported to be overexpressed in various cancer cell lines and human cancers." (PMID 33745968, 2021). "Overexpressed CDC25B has been reported in various cancer cell lines and human cancers." (PMID 33745968, 2021). "It was evident that CDC25B was an important oncogene to speed up cancer progression." (PMID 33442418, 2021). "Since these studies were conducted in cancer cells that have accumulated large chromosome aberrations, the cellular effects of CDC25B overexpression might depend on specific cellular context of cancer cells." (PMID 33745968, 2021). "However, the analysis also revealed that high Cdc25B levels have better survivals in lung and several other cancers, suggesting a tumor-suppressive function of Cdc25B." (PMID 33745968, 2021). "As CDC25B promotes cell cycle progression and is overexpressed in numerous rapidly dividing cancer cells, one might expect a correlation between CDC25B overexpression and the rate of proliferation." (PMID 33385163, 2020). "The top 1 network in the spleens of A.SW mice was categorized as “Cell Cycle,” “Reproductive System Development and Function,” and “Cancer,” including down-regulated genes: cyclin family (Ccne1, Ccnb1, and Ccnb2) and cell division cycle family (Cdc20, Cdc25b, and Cdc25c)." (PMID 30941144, 2019). "This upregulation of miR-141-3p and/or miR-200a-3p may have effects on several cancer-related target genes that have been previously associated with these two miRNAs, including E2F3, GLS, CCND2, PTEN, CCNG1, CDC25B, and ZFPM2." (PMID 28288173, 2017). "Taken together, our study indicates that KCTD12 exerts its effects in cancer by forming a complex with CDC25B and CDK1, and the phosphorylation of KCTD12 at serine 243 is necessary for the interaction of KCTD12 and CDK1, but it is not a crucial factor for the interaction with CDC25B." (PMID 28869606, 2017).
cancer (continued). "The oncogene CDC25B phosphatase plays an important role in cancer cell growth." (PMID 20813067, 2010). "Up-regulation of CDC25B expression has been documented in a variety of human cancers, however, the relationships with the alteration of the molecular mechanisms that lead to oncogenesis still remain unclear." (PMID 20128929, 2010). "As CDC25B promotes cell cycle progression and is over-expressed in numerous rapidly dividing cancer cells, CDC25B over-expression is expected to correlate with the rate of proliferation, consistent with our results that CDC25B siRNA suppressed proliferation of HCC cells." (PMID 18269767, 2008). "CDC25B is over-expressed in various types of human carcinomas, but the mechanism(s) regulating its expression remains unclear." (PMID 18269767, 2008). "Previous study has suggested the proto-oncogenic roles of FOXM1 and its downstream target genes Cyclin D1, Survivin and CDC25B in tumors, which include facilitating cell cycle progression and inducing tumor cell proliferation, as well as its relation with the poor prognosis of cancer patients." (PMID 35624501, 2022). "With its role in checkpoint control, Cdc25B overexpression might contribute to tumorigenic pathway by rapidly pushing cells into mitosis with incompletely replicated DNA, thus providing cancer cells with the ability to bypass checkpoint control to enhance their proliferation." (PMID 33745968, 2021). "Thus, the role of CDC25B in cancer might be more complicated than merely promoting cell cycle progression." (PMID 33385163, 2020). "Thus, in human malignant tumors, deficiency in Lats1 and/or Lats2 might promote overexpression of Cdc25B, leading to centrosome overduplication and, ultimately, to cancer progression." (PMID 26530630, 2015). "However, even though human Lats1 can interact with human Cdc25B, it remains unclear whether Lats1 is involved in centrosome duplication during interphase in human normal and/or cancer cells." (PMID 26530630, 2015). "Cdc25B and MKP‐1 proteins in human cancer cells showed promising results for treating cancer patients." (PMID 39434198, 2024). "The 14-3-3β has oncogenic roles in several different types of cancer cells through interactions with proteins such as Bad, FBI1, Raf-1, Cdc25b, and others." (PMID 37371348, 2023). "CircRNA profiling by microarray revealed a potential role of circ_IPCEF1 in PTC and showed interactions with four cancer-related genes, “CASR, CDC25B, NFκB1, and SHOC2” through sponging miR-3619-5p." (PMID 36230649, 2022). "In various types of cancers, numerous studies have now documented a link between EIF4A3, SMC3, ESPL1, CDC25B, CCNA2, or AURKA and their response to therapy." (PMID 32454908, 2020). "Understanding the molecular mechanism of how AMPK activity is regulated (such as by CDC25B and PP2A) provides better understanding the roles of AMPK in cancer development, progression as well as response to treatment." (PMID 33385163, 2020). "Yuning Song and colleagues previously reported a CDC25 inhibitor, CHEQ-2, that not only inhibited the catalytic dephosphorylation activity of CDC25A and CDC25B in vitro, but also down-regulated CDC25A and CDC25B levels in cancer cells." (PMID 31024841, 2019). "The cancer samples of patients with late-onset tumors presented higher YWHAE and MYC expression and lower CDC25B expression in relation to to early-onset GC samples (p<0.05 for all analyses)." (PMID 27863420, 2016). "In cancer cells, levels of phosphorylated p38 MAPK proteins are low whereas phosphorylated CDC25B protein levels are high." (PMID 25384584, 2015). "Additionally, the PARADIGM features corresponding to the genes CDC25B and DSN1 have higher activity in tumours with high NCS across many cancers." (PMID 35326573, 2022).
cancer (continued). "CDC25B mediates the rapamycin-induced activation of AKT, elF4E and p38 cascades, and CDC25B knockdown promotes the inhibitory effect of rapamycin on cancer cells growth through blocking cell cycle progression and inhibiting oncogenic pathways activation by rapamycin." (PMID 33385163, 2020). "Many cancers have been reported to overexpress CDC25A and CDC25B, but CDC25C has not previously been associated with cancer outcome." (PMID 27775025, 2016). "Unlike cdc25B, the incidence of cdc25A overexpression did not decrease in carcinomas with aggressive phenotypes." (PMID 12085185, 2002). "When compared with non-cancerous cells, CDC25A and CDC25B were strongly expressed in the cytoplasm of cancer cells, with positive (+) classification in 46% (46 cases) and 48% (48 cases), respectively." (PMID 11487274, 2001). "This functional role allows us to further determine that CDC25B and MCM complex workers coactivate the MAPK pathway, particularly the ERK and p38 signaling cascade to promote cell proliferation and differentiation, which plays an important role in subsequent cancer progression." (PMID 39371450, 2024). "Thus, the role of excess Cdc25B on tumorigenesis cannot not be fully determined using cancer cell lines." (PMID 33745968, 2021). "By comparing the lists of top-ranking cancer-related target genes, we were able to identify seven promising cancer-related genes that may be targets of the hsa_circRNA_100395/miR-141-3p/ miR-200a-3p axis in PTC (in order of descending rank): E2F3, GLS, CCND2, PTEN, CCNG1, CDC25B, and ZFPM2." (PMID 28288173, 2017). "However, the physiological roles of cdc25B in carcinomas do not appear to be simple." (PMID 12085185, 2002). "Thus, CDC25-inhibitors targeting either CDC25A or Cdc25B may have the useful property of exhibiting anti-tumor activity in those cancers overproducing these phosphatases without inducing the deleterious GI side effects associated with radiation and chemotherapy." (PMID 21283624, 2011).